SIRT3 (sirtuin 3)
Diseases named in the same sentence as SIRT3 in open-access papers (continued):
Sharing a sentence is not in itself a finding about the gene and the disease.
depression (13 papers, 2020 to 2025). "Depression in PD patients is associated with lower serum SIRT3 levels, right amygdala atrophy, decreased spontaneous activity in MidFG.L and SPL.L, and altered FC in the DMN and SN." (PMID 40259181, 2025). "For example, alterations in the expression of sirtuin 3 (SIRT3) are associated with the pathophysiology of depressive disorders." (PMID 36970275, 2023). "This integrated multi-omics and Mendelian randomization (MR) study provides the first population genetic evidence establishing dietary acrylamide (ACR) exposure as a risk factor for depression, primarily mediated through a SIRT3-dependent mitochondrial oxi-dative stress pathway." (PMID 41150784, 2025). "It is thought that SIRT3 may be a major regulator in the activation of the mitochondrial antioxidase to ameliorate depression associated with energy changes, such as that of menopause." (PMID 39404407, 2024). "This procedure aimed to clarify whether PE, a well-established inducer of SIRT3, could have any impact on an impaired neurogenesis-associated pathology, such as depression." (PMID 35011652, 2021). "However, these hypotheses remain preliminary, as this cross-sectional study cannot establish causality or mechanistic insights between SIRT3 reduction and depression in PD." (PMID 40259181, 2025). "Collectively, our findings provide initial evidence that may help reconceptualize ACR-associated depression as an environmentally triggered disorder driven by oxidative stress, offering a hypothetical rationale for targeting SIRT3 to mitigate dietary neurotoxicity." (PMID 41150784, 2025). "The genetic causality of JUN and PTK2 suggests that their activation in depression, upon ACR exposure, is likely an indirect consequence, mediated by the primary event of SIRT3 suppression and the resulting oxidative stress." (PMID 41150784, 2025). "Serum SIRT3 levels, total GMV/TIV ratios, and fALFF values of the MidFG.L and SPL.L demonstrate diagnostic utility for PD patients with depression, and their integration enhances diagnostic accuracy." (PMID 40259181, 2025). "The significance of SIRT3 dysregulation in depression pathogenesis is underscored by its role in preserving neurogenesis." (PMID 41150784, 2025). "Compared to healthy individuals, serum SIRT3 levels were lower in PD patients, especially in those with depression." (PMID 40259181, 2025). "This study examined changes in serum SIRT3 levels and used multimodal MRI to analyze the structural and functional brain characteristics of PD patients with depression to provide objective indicators for early diagnosis." (PMID 40259181, 2025). "Our findings demonstrate that ACR induces depression primarily through SIRT3 suppression, activating JUN/PTK2 pathways, suggesting its potential role in environmental toxicant-induced redox imbalance." (PMID 41150784, 2025). "Based on this, we investigated the changes in serum SIRT3 levels in PD patients with depression, as well as the particular brain structural and functional characteristics of PD patients with depression using multimodal MRI technology." (PMID 40259181, 2025). "Crucially, the strongest GA binding affinity was observed for SIRT3, which aligns with its significant dysregulation in the human depression transcriptome, suggesting SIRT3 as a primary target of GA-mediated toxicity." (PMID 41150784, 2025). "Previous research has demonstrated that SIRT3 plays a protective role in both PD and depression by maintaining mitochondrial homeostasis, reducing oxidative stress, and inhibiting neuroinflammation." (PMID 40259181, 2025). "The results indicate that serum SIRT3 levels were significantly lower in PD patients compared to healthy controls, with a more pronounced difference observed in those with depression." (PMID 40259181, 2025). "In psychiatric disorders such as depression, AC exhibits antidepressant potential, possibly through suppression of SIRT3/ROS‐mediated NLRP3 inflammasome activation." (PMID 40965425, 2025).
depression (continued). "Serum SIRT3 levels, total GMV/TIV ratios, and fALFF values of the MidFG.L and SPL.L have diagnostic value for PD patients with depression, and their combination can improve predictive accuracy." (PMID 40259181, 2025). "Taken together, we suggest Per3 ameliorates depressive disorder through modulating the NAMPT-controlled NAD+-SIRT3 pathway to regulate the mitochondrial energy metabolism in the hippocampus of mice." (PMID 39894345, 2025). "Within these rodent models of depression, using chronic unpredictable stress, animals demonstrate altered SIRT3 expression, and symptoms are ameliorated (at least partially) by upregulation of SIRT3 expression and lipid metabolism." (PMID 39404407, 2024). "In the depression model, SIRT3 can reduce ROS and activate NF-kB signals in the hippocampus of mice, thereby alleviating NLRP3-induced pyroptosis." (PMID 38044382, 2023). "In the future, further studies are needed to investigate the mechanism of SIRT3 and its role in diseases such as depression, in order to better understand its biological function and provide a basis for developing related therapeutic strategies." (PMID 37629568, 2023). "This study found that exercise can promote SIRT3 expression and exert antioxidant and anti-inflammatory effects to improve depression-like behavior." (PMID 37629568, 2023). "In order to further explore the relationship between Sirt3 and depression- and anxiety- like behaviors related menopause, we observed whether the overexpression of Sirt3 in the hippocampal neurons would affect the depression- or anxiety-like behaviors caused by VCD." (PMID 36290610, 2022). "The findings revealed the antidepressant property of α-Cyperone, and provided support for targeting SIRT3/ROS signaling in depression treatment." (PMID 33132912, 2020). "To bridge this knowledge gap, we hypothesized that dietary acrylamide (ACR) promotes depression through its epoxide metabolite GA, which mediates the suppression of SIRT3 function, leading to mitochondrial oxidative injury." (PMID 41150784, 2025). "Transcriptomic analysis of the human prefrontal cortex (datasets GSE54567 and GSE54568) revealed mitochondrial deacetylase sirtuin 3 (SIRT3) as the most significantly suppressed gene in depression (p < 0.01), suggesting an impairment in Superoxide dismutase 2 (SOD2)-mediated antioxidant defense." (PMID 41150784, 2025). "Notably, even in age-matched cohorts, SIRT3 levels in dPD patients remained significantly lower than those in HC, further highlighting depression as the central factor influencing SIRT3 levels." (PMID 40259181, 2025). "Our study identified a correlation between PD depression and serum SIRT3 levels, the total GMV/TIV ratios, the GMVs of AMYG.R, and fALFF values of the MidFG.L and SPL.L for the first time, suggesting possible marker for diagnostic depression in PD patients." (PMID 40259181, 2025). "We hypothesized that dietary ACR exposure promotes depression via SIRT3-dependent mitochondrial oxidative injury." (PMID 41150784, 2025). "Our integrated multi-omics analysis suggests a potential mechanistic link between dietary ACR exposure and the pathogenesis of depression, possibly mediated through SIRT3-dependent mitochondrial dysfunction, thereby addressing a significant knowledge gap in environmental neurotoxicology." (PMID 41150784, 2025). "Therefore, SIRT3 is recognized as pharmacological targets in neuropsychiatric disorders, such as depression." (PMID 39894345, 2025). "Therefore, investigating alterations in SIRT3 levels in PD patients with depression represents a significant research endeavor." (PMID 40259181, 2025). "Additionally, SIRT3 works in conjunction with SIRT1 and is highlighted in studies of resveratrol and its effect on depression preclinically, particularly when associated with mitochondrial dysfunction." (PMID 39404407, 2024).
depression (continued). "Therefore, the results of this study further support the view that exercise improves depression by upregulating SIRT3 expression to exert anti-inflammatory effects." (PMID 37629568, 2023). "In the future, further studies are needed to elucidate the mechanism of action of SIRT3 and its role in diseases such as depression, in order to better understand its biological functions and provide a basis for the development of relevant therapeutic strategies." (PMID 37629568, 2023). "However, exploring possible changes in lipidomics upon PE-, depression- and SIRT3-mediated effects appears to be of upmost importance for future studies." (PMID 35011652, 2021). "Altogether, these findings led us to hypothesize that exercise training increases the lipid metabolic rate, and that, under stress- and depression-like scenarios, SIRT3 cooperates with PE-induced LCAD to allow a proper neuronal differentiation process." (PMID 35011652, 2021). "Although it is possible that other SIRTs, such as SIRT1 and SIRT2, might also regulate neurogenesis, aging, and even depression, we decided to focus only on SIRT3 in this study, given its central role in mitochondrial metabolism and oxidative protection." (PMID 35011652, 2021). "Additionally, AICA Riboside intervention which restored hippocampal SIRT3 expression significantly ameliorated the depression-like and anxiety-like behaviors of CUMS mice." (PMID 33132912, 2020). "Taken together, these findings suggested that Cy has therapeutic potential for treating depression and that this antidepressant effect may be attributed to SIRT3 stimulated neuroplasticity enhancement by suppressing NLRP3 inflammasome." (PMID 33132912, 2020). "Additionally, the reduced SIRT3 levels might reflect that the presence of depression impairs SIRT3-mediated neuroprotection in PD." (PMID 40259181, 2025). "Given that SIRT3 is a master regulator of mitochondrial antioxidant defenses and energy metabolism, its suppression provides a plausible mechanistic link connecting ACR exposure to the mitochondrial oxidative damage observed in the brain, which is a hallmark of depression pathophysiology." (PMID 41150784, 2025). "Hence, here we sought to explore the molecular mechanisms underlying SIRT3’s regulation of the fate of NSCs, and whether SIRT3 and its downstream targets would be good pharmacological targets to rescue neurogenic potential in aging and depression contexts." (PMID 35011652, 2021). "Here, we aimed to explore the role of deacetylase Sirtuin 3 (SIRT3), a central player in mitochondrial metabolism and oxidative protection, in the fate of NSC under aging and depression-like contexts." (PMID 35011652, 2021). "Sirt3 depletion did not aggravate the depression and anxiety phenotype and hippocampal oxidant status induced by VCD, but partially abrogated the antidepressant and anxiolytic effects of kaempferol, as well as the antioxidant effects." (PMID 36290610, 2022). "In conclusion, our study reveals the specific mechanisms of Per3 ameliorates depressive disorder through modulating NAMPT-controlled NAD+ levels and highlight a critical role for Per3 in mitochondrial energy metabolism by impacting the BMAL1 compound through the NAMPT/NAD+-SIRT3 pathway." (PMID 39894345, 2025). "Our data revealed that MGO-induced depression like-behavior and memory deficits resulted from disturbances in Trp, 5-HT, BDNF, and NGF levels, increased p-Tau and APP expression, neuroinflammation, and impaired redox status (Nrf-2/Ho-1/TXNRD1/Sirt3/5) in the brain." (PMID 39574138, 2024).
depression (continued). "However, there are few experimental studies that have investigated whether exercise can intervene and regulate the pathological process of depression through the NLRP3 signaling pathway, particularly the SIRT3/ROS/NLRP3 axis." (PMID 37629568, 2023). "However, Cy treatment significantly restored the SIRT3/ROS/NF-κB pathway, and inhibition of SIRT3 led to the ablation of Cy generated protective efficacy in CUMS mice, suggesting the crucial role of SIRT3 signaling in the treatment of depression." (PMID 33132912, 2020). "As a previous study reported that overexpression of Bmal1 can up-regulate the expression of Sirt3 and Sod2, and reduce mitochondrial dysfunction induced by 3-MCPD, in conjunction with our findings, we suspected that SIRT3 might also be involved in the development of depression modulated by Per3." (PMID 39894345, 2025).
hyperlipidemia (13 papers, 2014 to 2026). "This suggests that decreased expression of Sirt3 can inhibit deacetylation, which is a common risk factor for both hyperlipidemia and ARHL." (PMID 35966796, 2022). "It has been reported that the liver contents of TG and cholesterol in Sirt3-knockout mice were significantly higher than those in the wild-type animals, resulting in accelerated obesity, insulin resistance, hyperlipidemia, and steatohepatitis." (PMID 37188264, 2023). "Taken together, VD/VDR upregulated SIRT3 and mitochondrial respiratory chain complexes, while decreasing hyperlipidemia-induced oxidative damage." (PMID 33981701, 2021). "Under hyperlipidemia, the inhibition of SIRT3 and the acetylation of mitochondrial protein leads to the excessive utilization of fatty acids as energy substrates in addition to excess oxygen consumption, in turn adversely affecting cardiac cells." (PMID 33981701, 2021). "Sirt3-KO mice on a high-fat diet showed accelerated progression of MetS, including hyperlipidemia." (PMID 35966796, 2022). "A significant decrease in Sirt3 expression was observed in mice with both hyperlipidemia and ARHL." (PMID 35966796, 2022).
Anxiety (12 papers, 2019 to 2025). Intense feelings of nervousness, tension, or panic often arise in response to interpersonal stresses. "Experiment on SIRT3 KO mice demonstrated that SIRT3 was essential for enhancing GABAergic synaptic transmission adaptability and counteracted anxiety during intermittent fasting." (PMID 40969935, 2025). "Intermittent fasting, which is known to increase SIRT3 levels, enhances GABAergic tone, reduces anxiety-like behaviors, and improves hippocampus-dependent memory in wild type but not in SIRT3-deficient mice." (PMID 36675125, 2023). "We found that SIRT3 attenuated postoperative anxiety by regulating SOD2 acetylation and mitochondria-mediated oxidative stress." (PMID 35372451, 2022). "Here, we showed that SIRT3 attenuated anesthesia/surgery-induced anxiety-like behavior in mice mPFC via the ac-SOD2 K68-mediated mitochondrial oxidative stress pathway." (PMID 35372451, 2022). "The role of other perioperative factors associated with the SIRT3 and HCN1 channels in the mPFC in postoperative anxiety behavior should be explored in the future studies." (PMID 35372451, 2022). "The protective effects of SIRT3 on anxiety-like behavior appeared to be related to HCN1 channel function." (PMID 35372451, 2022). "Both male and female Sirt3-KO mice displayed hyper-locomotion and attenuated anxiety-like behavior in response to a dose of amphetamine that was insufficient to promote any behavioural responses in wild-type mice." (PMID 36148309, 2022). "It has been previously reported that in mice AD model, IF has the beneficial effects on anxiety and cognition which is mediated by Sirt3 through increasing the enzymatic activity of SOD." (PMID 35624490, 2022). "This study was conducted to examine the effects of SIRT3 on anxiety-like behavior induced by anesthesia/surgery in mice and assess the role of HCN1 channels." (PMID 35372451, 2022). "These new data suggest that SIRT3 in hippocampal neurons is required to ameliorate anxiety-like responses to acute food deprivation in mice adapted to IF." (PMID 31015456, 2019). "The purpose was to assess the role of SIRT3 on postoperative anxiety like behavior in C57/BL6 mice." (PMID 35372451, 2022). "This study suggest that SIRT3 may ameliorate anesthesia/surgery-induced anxiety-like behavior by preventing SOD2 acetylation-mediated mitochondrial oxidative stress and HCN1 channel dysfunction in the mPFC of mice." (PMID 35372451, 2022). "Therefore, the relationship of SIRT3 on SOD2 acetylation, MMP reduction, and related HCN1 channel dysfunction in postoperative anxiety-like behavior and its underlying neuroprotective mechanism were studied in this research work." (PMID 35372451, 2022). "However, there are limited data on the impact of SIRT3 on anesthesia/surgery-induced anxiety-like behavior of mice." (PMID 35372451, 2022). "SIRT3 overexpression attenuated postoperative anxiety in mice." (PMID 35372451, 2022). "SIRT3 attenuated anesthesia/surgery induced anxiety emotion in mice was indicated by these data." (PMID 35372451, 2022). "In light of our findings that the beneficial effects of IF on anxiety and cognition are mediated by SIRT3, it will be of interest to determine whether SIRT3 also mediates the anxiolytic and cognition-enhancing effects of exercise." (PMID 31015456, 2019). "In contrast to the anxiolytic effect of IF in wild type mice, results of open field and elevated plus maze tests showed that the anxiety response to FD was not ameliorated by IF in SIRT3-deficient (Sirt3–/–) mice." (PMID 31015456, 2019). "Our results revealed that SIRT3 might have an important regulatory function in the HCN1 channel through the SOD2 acetylation-mediated mitochondrial pathway in a mouse model of postoperative anxiety." (PMID 35372451, 2022). "We found that SIRT3 level reduced and HCN1 expression level increased in mice medial prefrontal cortex (mPFC) as well as anxiety like behavior postoperatively." (PMID 35372451, 2022).
Anxiety (continued). "Several studies have reported that the HCN1 channel is related to anxiety in different disease models, but no studies have evaluated HCN1 channels in anesthesia/surgery-induced anxiety-like behavior and the dependence of HCN1 channel on SIRT3." (PMID 35372451, 2022). "The study demonstrated that mice lacking SIRT3 in the hippocampal neurons have heightened anxiety, poor memory retention, and impaired long-term potentiation at hippocampal synapses." (PMID 37960975, 2023). "As WT mice receiving higher doses of AMPH (3.0 mg/kg) also display decreased anxiety-like behaviour in the same elevated plus maze task, these results further indicate the absence of Sirt3 sensitizes mice to AMPH-induced behavioural responses." (PMID 36148309, 2022). "Both male and female Sirt3-KO mice displayed heightened sensitivity to AMPH-induced behavioural responses in both tasks, and both sexes demonstrated the same magnitude of hyperactivity and diminished anxiety-like behaviour in response to a low dose of AMPH." (PMID 36148309, 2022). "Mice lacking SIRT3 in hippocampal neurons did not adapt to long term IF as indicated by heightened anxiety and relatively poor memory retention in behavioral tests, and by impaired long-term potentiation at hippocampal synapses." (PMID 31015456, 2019). "Furthermore, the HCN1 channel inhibitor ZD7288 significantly protected against anesthesia/surgery-induced anxiety, but without SIRT3/ac-SOD2 expression or oxidative stress changes." (PMID 35372451, 2022). "Our results suggest that SIRT3 may achieve antianxiety effects through regulation of SOD2 acetylation-mediated oxidative stress and HCN1 channels in the mPFC, further strengthening the therapeutic potential of targeting SIRT3 for anesthesia/surgery-induced anxiety-like behavior." (PMID 35372451, 2022).